BRCA1 (BRCA1 DNA repair associated)
Diseases named in the same sentence as BRCA1 in open-access papers (continued):
Sharing a sentence is not in itself a finding about the gene and the disease.
breast cancer (continued). "To assess whether broader defects on heterochromatin are specifically associated with BRCA1-deficit, we evaluated the features of whole heterochromatin in two breast cancer cell lines with different BRCA1 constitution, MCF7 (BRCA1wt) and HCC1937 (BRCA1−/−)." (PMID 19440381, 2009). "We are currently testing this by sequencing the APC gene around codons 1500–1700 in hereditary breast cancer patients which tested negative for BRCA1/BRCA2 germline mutations." (PMID 19578404, 2009). "According to the Breast Cancer Information Core (BIC) database, about two thirds of germline variants identified in BRCA1 and BRCA2 are unique; the remaining ones are recurrent founder mutations which have been described in different ethnic groups and populations." (PMID 19619314, 2009). "However, despite the identification of mutations in the major risk factor genes such as BRCA1, BRCA2, PTEN, CHEK2, and ATM, it is estimated that ~75% of familial breast cancers have yet unidentified risk alleles." (PMID 20003447, 2009). "Bond, Levine and colleagues studied the effects of SNP309 G/G on breast cancer onset age in a group of Ashkenazi breast cancer patients who were not BRCA1/2 carriers of mutations." (PMID 19226467, 2009). "In conclusion, women from high-risk breast cancer families in which a BRCA1 or BRCA2 mutation can not be found need to be counselled about their increased risk for breast cancer." (PMID 19088722, 2009). "Until recently, the molecular mechanisms explaining increased incidence of ovarian and breast cancers in carriers of BRCA1 gene mutations had not been clearly understood." (PMID 19445691, 2009). "In summary, microarray profiling of untreated whole blood does not appear to be informative in identifying breast cancer risk due to BRCA1 mutation." (PMID 19352458, 2009). "We previously reported two SNPs in SRC-3 (rs2230782 and rs2076546) associated with reduced breast cancer risk in a case-control study of German and Polish high-risk, BRCA1/2 mutation-negative women (cases: 775, controls: 1628)." (PMID 20003447, 2009). "In this study, we estimate the breast cancer risks for women with a strong family history of breast cancer, but tested negative for a mutation in BRCA1 or BRCA2." (PMID 19088722, 2009). "In this prospective study, we estimate breast cancer risks in women with a family history of breast cancer and for whom the proband tested negative for a mutation in BRCA1 or BRCA2." (PMID 19088722, 2009). "Whatever interpretation one may choose, the findings were that stage 1 breast cancer in BRCA1 carriers has a poor prognosis." (PMID 19366445, 2009). "To determine whether the increased EZH2 levels are functionally relevant in the BRCA1-deficient tumor cells, we made use of cell lines that were derived from KB1P and KP mouse mammary tumors." (PMID 19709408, 2009). "BRCA1 mutant HCC1937 breast cancer cells were previously shown to be deficient in the DNA decatenation checkpoint and that this checkpoint is restored in HCC1937 cells with reconstituted wild type BRCA1 expression." (PMID 19128485, 2009). "Hereditary breast cancer (e.g. BRCA1 and 2 mutations) is more frequent in young women with breast cancer but this has not implied a worse survival in most studies." (PMID 19907646, 2009). "Most human BRCA1-mutated breast cancers are ‘triple-negative’ tumours that do not express ER, PR and ERBB2." (PMID 19904273, 2009). "On July 23, 2008, Breast Cancer Research and Treatment journal released an electronic publication ahead of print of the first-ever breast cancer (BC) study, which specifically selected BRCA1-carriers for the neoadjuvant treatment and used monotherapy by cisplatin instead of conventional schemes." (PMID 19379506, 2009).
breast cancer (continued). "Our results also imply that recommendation of full screening of the BRCA1 and BRCA2 genes, and even additional predisposing genes, to all breast cancer patients should remain the ultimate goal as new technologies emerge that can lower the cost and effort involved." (PMID 19491894, 2009). "The availability of rapid genetic testing for BRCA1 and BRCA2 mutations has made it possible to follow unaffected carriers in greater numbers and to search for inherited mutations in women with a severe family history of breast cancer." (PMID 19718449, 2009). "Tumour subclasses differed considerably in terms of presence/absence of angioinvasion, which leads us to speculate that these genes have a function in the prognosis of ER-negative BRCA1 breast cancer." (PMID 19826428, 2009). "In addition, we evaluated the occurrence of broader defects of heterochromatin in relation to BRCA1 status in breast cancer cells." (PMID 19440381, 2009). "Relation between breast cancer receptorial status and BRCA1 mutant genotype." (PMID 19818148, 2009). "Finally, we evaluated the occurrence of broader defects of heterochromatin in breast cancer cells in relation to BRCA1 status." (PMID 19440381, 2009). "In contrast to women with heterozygous BRCA1 germline mutations, none of the heterozygous Brca1 mouse mutants developed spontaneous mammary tumours." (PMID 19904273, 2009). "We followed a similar approach by genotyping candidate SNPs for associations with breast cancer risk in a high-risk, BRCA1/2 mutation-negative case-control study; however, the original study was extended in three ways." (PMID 20003447, 2009). "However, we found that global heterochromatin defects are present in breast cancer cell lines independently of BRCA1 status." (PMID 19440381, 2009). "Despite GENECARD families being selected on early age-of-onset, genetic heterogeneity manifest as differences in age-of-onset could still be present, as observed in the discovery of the BRCA1 breast cancer gene." (PMID 19119412, 2009). "About 30% to 40% of sporadic breast cancers, which represent the vast majority (90% to 95%) of breast cancer cases, exhibit lower or absent levels of BRCA1 in the absence of mutations in the BRCA1 gene." (PMID 18377656, 2008). "Since the discovery of BRCA1 and BRCA2, numerous genes have been associated with a moderate increase in risk and are thought to interact in a polygenic inheritance mode to increase the susceptibility for breast cancer." (PMID 19077293, 2008). "Gene expression analysis of individual Brca1 mammary tumors and their subsequent passages in vivo revealed substantial heterogeneity in gene expression, as predicted by differences in frequency and identity of cancer stem cell populations in cell lines derived from these tumors." (PMID 18241344, 2008). "The results of our investigation showed that BRCA1 mutation carriers were more likely to have ERα-negative breast cancer than those in the control group." (PMID 18405391, 2008). "As deleterious germline mutations in BRCA1 and BRCA2 confer a greatly increased risk of breast cancer, some sequence variants in both genes might be candidates for moderate or low penetrance alleles." (PMID 18489799, 2008). "We found that that same Brca1-deficient genetic background gave rise to mammary tumors with two distinct and non-overlapping populations of cells that bear cell surface markers previously assigned to tumor-initiating cells from human breast and other organs." (PMID 18241344, 2008). "Even including 40% of the follow up time and 80% of the breast cancers from the FDR unknown category, this still gave an annual incidence of breast cancer of 1.98% for both BRCA1/2 mutation carriers (38/1917; 35/1763.6)." (PMID 18513387, 2008).
breast cancer (continued). "In our study as well, CK-14 was significantly associated with BRCA1 carrier status, and CK-5/6 frequency was also higher than among sporadic breast cancers but the difference was not statistically significant." (PMID 18275599, 2008). "We found that BRCA1 and BRCA2 samples were more similar to each other than to familial breast cancer patients without BRCA1/2 mutations, and that the type of sequence change in BRCA1 and BRCA2 (missense or truncating) influenced gene expression." (PMID 18497862, 2008). "As deleterious germline mutations in BRCA1 and BRCA2 confer a greatly increased risk of breast cancer, some sequence variants may be only moderate or low penetrant alleles." (PMID 18489799, 2008). "It would be important to determine whether other BRCA1-deficient human and mouse tumors with EMT features are enriched in putative breast cancer stem cells." (PMID 18394172, 2008). "We further evaluated the 5557G>A missense variant and the IVS38-8T>C and the IVS24-9delT polymorphisms, for breast cancer risk in a subgroup of 126 familial breast cancer cases without BRCA1/2 mutations and in 200 healthy controls." (PMID 18433505, 2008). "Since there was a clear correlation between the CD44+/CD24- status and the basal-like tumor subtype, we extended the immunohistochemical analysis to an additional TMA including tumors from BRCA1 hereditary breast cancer patients, known to be of predominantly basal-like phenotype." (PMID 18559090, 2008). "We compared expression profiles of irradiated LCLs from BRCA1 and BRCA2 carriers to those of non-BRCA1/2 BRCAX familial breast cancer patients, an appropriate reference group for the proposed evaluation of unclassified variants identified in familial breast cancer patients." (PMID 18497862, 2008). "Genotype and allele frequencies of IVS24-9delT, IVS38-8T>C and 5557G>A ATM variants in BRCA1/2 negative breast cancer cases and controls." (PMID 18433505, 2008). "Thus, serial transplantation of Brca1 mammary tumors resulted in minimal gene expression profile changes." (PMID 18394172, 2008). "Subsequently, these results will be crucial in the characterization of the genetic breast cancer susceptibility profile, within familial breast cancer cases non-carriers of BRCA1/BRCA2 mutations." (PMID 18230179, 2008). "Although our study confirms that basal CKs can help to identify BRCA1 mutation carriers, this effect was weaker than previously suggested and CKs did not independently predict BRCA1 mutation either from sporadic or familial breast cancer cases." (PMID 18275599, 2008). "It is noteworthy that in our clinical material (in contrast to ERα) the expression of the ERβ in tumor tissues of patients with BRCA1 gene mutations is almost as frequent as in the non-hereditary breast cancer patients." (PMID 18405391, 2008). "Patients with either BRCA1 or BRCA2 germ-line mutations have an average risk of 39% and 11% respectively of developing ovarian cancer by the age of 70; they have a risk of 35-85% of developing breast cancer in their lifetime." (PMID 22275985, 2008). "Polyphen was particularly better at isolating BRCA1 UV carriers likely to have a family history of breast cancer or ovarian cancer, and may therefore help to classify BRCA1 UVs." (PMID 18284688, 2008). "It has been pointed out in many studies that BRCA1 positive breast cancers rarely express ERα." (PMID 18405391, 2008). "Composite genotype frequencies for IVS24-9delT, IVS38-8T>C and 5557G>A ATM variants in BRCA1/2 negative breast cancer cases and controls." (PMID 18433505, 2008). "Brca1-deficient mouse mammary tumors harbor heterogeneous cancer stem cell populations, and CD44+/CD24- cells represent a population that correlates with human breast cancer stem cells." (PMID 18241344, 2008).
breast cancer (continued). "To determine whether Brca1 cell lines contain a distinct population of cancer stem cells, we examined expression of cell surface markers previously assigned to human breast cancer stem cells, namely CD44 and CD24." (PMID 18241344, 2008). "In spite of having a similar size at the time of collection (approximately 1 gm of wet weight), heterogeneity of Brca1 mammary tumors was also evident upon pathological examination of morphology, immunohistochemistry, and immunofluorescence analysis of tumor markers." (PMID 18394172, 2008). "We examined the peripheral blood and tumour DNA of KCF3 for methylation at other loci that are commonly methylated in breast cancer to assess whether the observed BRCA1 methylation was due to a propensity to methylate at a global level." (PMID 18269736, 2008). "Because altered regulation of BRCA1 may increase the likelihood of developing breast cancer, it is important to examine the molecular events that regulate normal BRCA1 expression." (PMID 18377656, 2008). "In addition, male BRCA1 and (to a greater extent) BRCA2 carriers are at an increased risk of developing breast cancer, (DF Easton, unpublished data)." (PMID 18349832, 2008). "For example, if such a system saw that BRCA1 and breast cancer occurred in the same sentence, it might assume a relationship between breast cancer and the BRCA1 gene." (PMID 18225946, 2008). "The differences in age of diagnosis of breast cancer in the BRCA1 and BRCA2 mutation-positive groups did not permit the combined analysis of these groups versus mutation-negative group." (PMID 18402691, 2008). "Subsequent population-based studies have shown that a recurrent loss of function CHEK2 mutant, CHEK21100delC is present in approximately 1% of the population and in 5% of familial breast cancer families lacking a BRCA1 or BRCA2 mutation." (PMID 18797466, 2008). "Breast cancers (BC) in women carrying mutations in BRCA1 gene are more frequently estrogen receptor negative than the nonhereditary BC." (PMID 18405391, 2008). "In BRCA1-mutant breast cancer cells, reconstitution of BRCA1 resulted in the cisplatin resistance." (PMID 19690636, 2007). "Both scenarios would explain the unsuccessful attempts to identify other breast cancer predisposition genes different from BRCA1 and BRCA2, due to lack of power." (PMID 17760956, 2007). "Many of the known hereditary breast cancer genes such as BRCA1, BRCA2, CHEK2, ATM, and FANCJ/BRIP1 work together in a DNA repair pathway, raising the possibility that other genes in this pathway also predispose to breast cancer." (PMID 18053174, 2007). "Germline mutations in BRCA1 (OMIM 113705) and BRCA2 (OMIM 600185) account for familial clustering in the majority of families with both breast and ovarian cancer and in approximately one-half of families with site-specific breast cancer." (PMID 17603881, 2007). "Common polymorphic variants in BRCA1 and BRCA2 genes may represent breast cancer (BC) susceptibility alleles and could be associated with a modestly increased risk of MBC at population level." (PMID 17767707, 2007). "In order to evaluate the power improvement provided by using SNP markers in a real situation, we have performed a whole genome screen of 19 non-BRCA1/2 breast cancer families using 4720 genomewide SNPs with Illumina technology (Illumina's Linkage III Panel), with an average distance of 615 Kb/SNP." (PMID 17760956, 2007). "The BRCA1 tumour suppressor gene plays a central role in the development of breast cancer." (PMID 17663789, 2007). "We found that women were compliant for 75% of their follow-up, but valid reasons like pregnancies or breast cancer treatments may partly explain why these BRCA1/2 carriers missed or delayed their annual screening visits." (PMID 17426707, 2007).